HOXB4 (homeobox B4)
Diseases named in the same sentence as HOXB4 in open-access papers (continued):
Sharing a sentence is not in itself a finding about the gene and the disease.
cyst (1 paper, 2009). A sac-like closed membranous structure that may be empty or contain fluid or amorphous material. "The increased synthesis of Hoxb4 protein in Prep1i/i oocytes agrees with the hypothesis that the absence of Prep1 relieves a block of Hoxb4 mRNA translation leading to an oocyte growth failure and cyst formation." (PMID 19365557, 2009).
glioma (1 paper, 2021). A benign or malignant brain and spinal cord tumor that arises from glial cells (astrocytes, oligodendrocytes, ependymal cells). "Our results showed that 25 of the differentially expressed URGs were related to survival in glioma patients; six genes, CDC20, UBE3C, WDR62, DTL, HOXB4, and TRIM38, were statistically significant with an AUC value greater than 0.7." (PMID 33914773, 2021). "Univariate analysis and multivariate analysis of the correlation of the expression of CDC20, UBE2C, WDR62, DTL, HOXB4 and TRIM38 with OS among glioma patients." (PMID 33914773, 2021).
lymphopenia (1 paper, 2013). Reduction in the number of lymphocytes. "Moreover, overexpression of Hoxb4 promoted the enrichment of CD62L positive cells following lymphopenia induced proliferation." (PMID 24324706, 2013).
malignant mesothelioma (1 paper, 2022). A malignant neoplasm of the pleura or peritoneum, arising from mesothelial cells. "Meanwhile, HOXB4 transcription factors are potential targets and markers in malignant mesothelioma." (PMID 35211403, 2022).
mesothelioma (1 paper, 2016). A usually malignant and aggressive neoplasm of the mesothelium which is often associated with exposure to asbestos. "We also found that there was a positive, linear relationship between HOXB4 expression and tumor growth in a mouse model of human mesothelioma." (PMID 26867567, 2016). "Our findings indicate that the HOX genes are widely dysregulated and often strongly upregulated in mesothelioma, and that elevated HOXB4 expression predicts shorter OS in mesothelioma patients." (PMID 26867567, 2016). "HOX genes are a potential therapeutic target in mesothelioma, and HOXB4 expression correlates with overall survival." (PMID 26867567, 2016). "From a practical view point, there are currently no reliable markers of OS in mesothelioma, and the use of HOXB4 as a prognostic marker in this context therefore justifies further evaluation." (PMID 26867567, 2016).
myeloid malignancies (1 paper, 2018). "Six epigenetic regulators were sequenced in 39 patients with myeloid malignancies and levels of HOXB4 and miR-10a were measured." (PMID 30419846, 2018).
osteosarcoma (1 paper, 2022). A usually aggressive malignant bone-forming mesenchymal neoplasm, predominantly affecting adolescents and young adults. "After that, FAGs in the turquoise module were utilized to construct a prognostic multigene (COL5A2, HOXB4, and UNC5B) signature for risk stratification in osteosarcoma." (PMID 36330451, 2022). "The HOXB4 protein was found in more than 90% of neoplastically transformed cells in osteosarcoma; however, its significance is still unknown and requires further research." (PMID 36330451, 2022). "In TCGA cohort, Kaplan–Meier survival analysis revealed that increased COL5A2 and UNC5B expression indicated a worse prognosis in patients with osteosarcoma, but HOXB4 expression was not linked with patients’ clinical fate." (PMID 36330451, 2022). "A total of three FAGs, COL5A2, HOXB4, and UNC5B, were ultimately used to construct a prognostic signature for osteosarcoma." (PMID 36330451, 2022). "We identified three FAGs (COL5A2, HOXB4, and UNC5B) as potential therapeutic targets and important regulators of ferroptosis in osteosarcoma." (PMID 36330451, 2022). "We also identified COL5A2, HOXB4, and UNC5B as potential therapeutic targets and important regulators of ferroptosis in osteosarcoma." (PMID 36330451, 2022). "Consistent with the RNA-seq data, the mRNA levels of COL5A2 and HOXB4 were lower and UNC5B mRNA levels were higher in RSL3-treated cells than in control cells, indicating the probable roles of the three FAGs in the ferroptotic processes of osteosarcoma cells." (PMID 36330451, 2022).
squamous cervical cancer (1 paper, 2021). "The HOXB4 mRNA expression in 10 normal cervical specimens was 30.6 (9.5–52.7) detected by qRT-PCR, which was higher than the level of 14 specimens of squamous cervical cancer [7.7 (3.3–12.2)] (95% CI, P = 0.0155)." (PMID 33479226, 2021). "In this study, HOXB4 was determined to be downregulated in cervical squamous cell carcinoma." (PMID 33479226, 2021).
T-cell leukemia (1 paper, 2024). A malignant disease of the T-lymphocytes in the bone marrow, thymus, and/or blood. "The cooperation between E2A-PBX1 and HOX also has a certain contribution to the induction of T cell leukemia, as T cell leukemia in Hoxb4 compound transgenic animals is more obvious." (PMID 39129784, 2024).
cancer (17 papers, 2011 to 2025). A tumor composed of atypical neoplastic, often pleomorphic cells that invade other tissues. "Analysis of enriched genes both in the MC-LR induced-pathways in cancer and the HOXB4-correlation transcription genes identified C-myc as a key target associated with HOXB4 high expression." (PMID 35211403, 2022). "HOXB4 has also been implicated as a cancer-related gene in other malignancies including breast cancer, leukaemia, osteosarcoma and lung cancer." (PMID 21906307, 2011). "Furthermore, we also observed a positive correlation of HOXB4 expression with the estimated infiltration value of cancer-associated fibroblasts in COAD." (PMID 35211403, 2022). "To further study the effect of HOXB4 combined with multiple indicators on cancer prognosis, we created a nomogram for predicting the OS, DSS, and PFI of COAD patients in the TCGA cohort." (PMID 35211403, 2022). "HOXB4, a member of the homeobox gene family, is a transcription factor involved in stem cell self-renewal and cancer." (PMID 36330451, 2022). "To explore the oncogenic role of human HOXB4, we used the public database, TCGA, to analyze the mRNA expression of HOXB4 in various types of cancer." (PMID 35211403, 2022). "We adopted multiple immune deconvolution methods to find a statistically positive correlation of HOXB4 expression with B cells, macrophages, CD8+ T cells, CD4+ T cells, dendritic cells, neutrophils, and cancer-associated fibroblasts." (PMID 35211403, 2022). "Mice engrafted with HOXB4-overexpressed cancer cells had smaller tumor volumes throughout the experiment than mice engrafted with control cells." (PMID 33479226, 2021). "HOXB4 has been reported to contribute to tumorigenesis in many cancers." (PMID 33634306, 2021). "However, some studies have shown that HOXB4 was downregulated in cancer tissues and reduced in vitro cell proliferation and migration." (PMID 33479226, 2021). "HOXB4 plays a vital role in proliferation, metastasis, and angiogenesis in cancers." (PMID 34620221, 2021). "Although HOXB4 overexpression is significantly correlated with cancer progression and poor prognosis, the precise mechanism of HOXB4 in OV remains unclear." (PMID 32178630, 2020). "Previous studies indicated that HOXB4 plays a crucial role in cancer progression." (PMID 32178630, 2020). "HOXB4 plays an important role in proliferation, metastasis, and angiogenesis in cancer." (PMID 32178630, 2020). "Homeobox B4 (HOXB4) is correlated with poor prognosis of various cancer types." (PMID 32178630, 2020). "In addition, HOXC4 triggers similar molecular alterations as HOXB4 and also is involved in some cancers." (PMID 28852427, 2017). "Here, our observations outline that HOXB4 internalization in hEB-derived cells could modulate the expression of some genes that regulate stem cells and cancer cells, transcription, cell cycle progression, developmental events or cell differentiation." (PMID 22761810, 2012). "Hence, HOXB4 may serve as a tumor suppressor gene or an oncogene, depending on the specific cancers." (PMID 33479226, 2021). "In addition, HOXB4 is a key regulator of NK cell function, and its application in the generation of functional NK cells with increased lytic potential may be of great significance for cancer immunotherapy." (PMID 35211403, 2022). "The results showed that some HOX genes in pan-cancer had significant strong correlation (R≥0.8): HOXA9 with HOXA10, HOXB5 with HOXB6 and HOXB8, HOXB8 with HOXB6 and HOXB9, HOXB3 with HOXB4 and HOXB5 and HOXB6, HOXC8 with HOXC9, HOXC9 with HOXC10, HOXD10 with HOXD11." (PMID 39980564, 2025). "HOXB4 acts as a transcription factor to directly evoke or inhibit the expression of genes including Snail, Twist, and MMP3 involved in regulation of carcinogenesis and cancer metastasis." (PMID 35211403, 2022).
tumor (11 papers, 2016 to 2024). "Meanwhile, studying the association of MC-LR exposure and HOXB4 levels with tumor stage and prognosis of CRC and exploring the underlying molecular mechanism would be beneficial as well." (PMID 35211403, 2022). "In the TCGA database analysis, the TPM (tumor mutation burden) from RNA-seq revealed the variable expression of HOXB4 in OV tissues." (PMID 32178630, 2020). "The tumors of patients surviving less than 6 months had a significantly higher expression of HOXB4 (p = 0.0166), and likewise a Kaplan-Meier analysis of overall survival (OS) showed that high HOXB4 tumor expression was associated with a significantly shorter OS (p = 0.041)." (PMID 26867567, 2016). "Together, these results further implied that HOXB4 was the key molecule for mediating MC-LR activation in the tumor immune infiltration and tumor microenvironment." (PMID 35211403, 2022). "At 38 days after tumor cell implantation, we observed a 94.4% decrease in the size and a 96.5% decrease in the weight of the tumors formed by HOXB4-overexpressed HeLa cells compared with those of the control tumors." (PMID 33479226, 2021). "HOXB4, a member of the Antp homeobox protein family, regulates embryonic development and participates in tumor progression as an oncogene or tumor suppressor gene." (PMID 33479226, 2021). "On day 48, compared to the control mice, mice implanted with HOXB4-depleted SiHa cells showed larger tumor volumes, with a 17.1-fold increase in tumor size and a 5.8-fold increase in tumor weight; these mice also had shortened tumor-free survival." (PMID 33479226, 2021). "Western blot results showed that the protein level of HOXB4 was upregulated in randomly selected paired tumor specimens." (PMID 32178630, 2020). "Mechanistically, HOXB4 enhances the proliferation and invasion of tumor cells by activating DHDDS, thereby promoting the malignant progression of OV." (PMID 32178630, 2020). "We also found that the high expression of HOXB4 in OV tissue was positively associated with clinical stage, pathologic grade, and TMB (tumor mutation burden) of OV." (PMID 32178630, 2020). "A xenograft tumor model was generated in nude mice to detect the role of HOXB4 in tumor proliferation and metastasis." (PMID 32178630, 2020). "In tumors from mice injected with PBS only, we found a significant, linear relationship between the expression of HOXB4 and final tumor size (r2 = 0.8278; p = 0.0321)." (PMID 26867567, 2016). "In several forms of solid tumors, HOXB4 acts as both an oncogene and a tumor suppressor." (PMID 36330451, 2022). "These analysis results may aid the insight to the role of HOXB4 in MC-LR mediated-CRC progression from the perspective of clinical tumor sample studies." (PMID 35211403, 2022). "IHC results revealed the high expression level of HOXB4 in OV tumor tissues." (PMID 32178630, 2020). "The role of HOXB4 in contributing to tumor development in vivo was verified in mice." (PMID 32178630, 2020). "Notably, HOXB4 overexpression significantly extended the tumor-free survival of animal." (PMID 33479226, 2021). "IHC staining of tumor tissues demonstrated invasion and metastasis, and EMT markers were upregulated following overexpression of HOXB4 and DHDDS." (PMID 32178630, 2020). "We assessed the probable relationship between the HOXB4 expression and the infiltration stage of different immune cells in COAD from TCGA by using TIMER2.0, to find out whether HOXB4 regulates the tumor microenvironment." (PMID 35211403, 2022). "When HOXB4 and DHDDS were individually overexpressed, tumor growth was significantly enhanced." (PMID 32178630, 2020). "Conversely, when HOXB4 downstream of DHDDS was blocked, tumor growth was inhibited." (PMID 32178630, 2020). "Similarly, 45/49 and 36/48 LAC cases compared to 3/31 and 0/31 tumor-adjacent normal lung samples showed hypermethylation of the SIM1 and HOXB3/HOXB4 regions, respectively." (PMID 27782156, 2016).
hematological malignancies (1 paper, 2018). "Moreover, miR-10a and HOXB4 overexpression seemed associated with DNMT3A mutation in hematological malignancies." (PMID 30419846, 2018). "Having established the epigenetic regulation of HOXB4/MiR-10a expression, we wondered whether the expression level of these genes may correlate with the mutational status of epigenetic modifiers frequently mutated in hematological malignancies." (PMID 30419846, 2018).
HOXB4 also shares sentences with these, for which no sentence is quoted: acute myocardial infarction (1 paper); clear cell renal cell carcinoma (1); congenital heart defects (1); craniosynostosis (1); gastric cancer (1); glioblastoma (1); head and neck squamous cell carcinoma (1); idiopathic thrombocytopenic purpura (1); insulinoma (1); lung squamous cell carcinoma (1); pancreatic cancer (1); pancreatic ductal adenocarcinoma (1); renal carcinoma (1); Sepsis (1); serous ovarian cancer (1); squamous cell carcinoma (1); uterine corpus endometrial carcinoma (1).